PTENP1 (phosphatase and tensin homolog pseudogene 1)
Diseases named in the same sentence as PTENP1 in open-access papers (continued):
Sharing a sentence is not in itself a finding about the gene and the disease.
hepatocellular carcinoma (25 papers, 2015 to 2026). A malignant tumor that arises from hepatocytes. "This study investigated the clinical significance and predictive value of two biologically antagonistic lncRNAs, UFC1 and PTENP1, as circulating biomarkers for hepatocellular carcinoma (HCC) in an Egyptian cohort." (PMID 42042020, 2026). "Other studies in esophageal carcinoma, head and neck squamous cell carcinoma, hepatocellular cancer and oral squamous cell carcinoma have confirmed the impact of PTENP1 up-regulation on attenuation of tumor growth." (PMID 35655204, 2022). "Hepatocellular carcinoma (HCC) cell-derived exosomes (HCC-Exos) carrying the miR-21 molecule promote the proliferation of HCC cells by inhibiting the expression of PTENp1 and PTEN." (PMID 35571530, 2022). "Recent data has also revealed that exosomal miR-21 can regulate the TETs/PTENp1/PTEN pathway to promote cell growth in hepatocellular carcinoma." (PMID 34572835, 2021). "One of the pseudogenes named PTENP1, down-expressed in Hepatocellular carcinoma (HCC) cells and showed the anti-carcinoma properties due to its ability to regulate cellular levels of its parent gene (PTEN)." (PMID 29291003, 2017). "Sleeping Beauty transposon containing baculovirus was also recently coupled with PTENP1 long non-coding RNA (lncRNA) which inhibited cell proliferation in hepatocellular carcinoma cells (HCC) in vitro and HCC tumors in mice." (PMID 25912715, 2015). "Some research also indicates that the overexpressed PTENP1 in hepatocellular carcinoma (HCC) competitively binds with miR-17, miR-19b, and miR-20a to promote the ULK1, ARG7, and p62 autophagic genes to complete the autophagy process and to suppress HCC progression." (PMID 35097120, 2022). "In hepatocellular carcinoma, the lncRNAs phosphatase and tensin homolog pseudogene 1 (PTENP1) activate autophagy, interacting with miR-17, miR-19b, and miR-20a, denying their targeting of the autophagy genes ULK1, ATG7 and p62/SQSTM1, and the tumor suppressor PTEN." (PMID 33194736, 2020). "Several tests have been conducted, including injecting rod-shaped viruses carrying PTENP1 into hepatocellular carcinoma (HCC) cells, which led to increased PTENP1 levels in these cells." (PMID 40877546, 2025). "Comprehensive model validation: Model predictions versus established experimental observations of miR-21, PTEN, and PTENP1 in breast, hepatocellular carcinoma (HCC) and oral squamous cell carcinoma (OSCC)." (PMID 39125832, 2024). "Transfection of baculovirus packaged PTENP1 into hepatocellular carcinoma (HCC) cells resulted in increased PTENP1 levels in cells." (PMID 37894321, 2023). "Pseudogene PTENP1 repressed the oncogenic PI3K/AKT pathway and inhibited hepatocellular carcinoma (HCC) progression." (PMID 34660259, 2021). "LncRNA PTENP1 (Long non-coding RNA PTENP1), a pseudogene of the tumor suppressor gene PTEN, induces autophagy as a pro-death response to suppress hepatocellular carcinoma." (PMID 28915706, 2017). "Recently, accumulating evidences revealed that PTENP1 was downregulated or deleted in various cancers, such as GC, hepatocellular carcinoma (HCC), renal cell carcinoma, head and neck squamous cell carcinoma (HNSCC), melanoma, endometrial cancer, and oral squamous cell carcinoma (OSCC)." (PMID 28931965, 2017). "In addition, studies indicate that lncRNA PTENP1 suppresses the oncogenic PI3K/AKT pathway in hepatocellular carcinomas, and can be used to treat hepatocellular carcinomas via miRNAs such as miR-17, miR-19b, and miR-20." (PMID 36831110, 2023). "However, the precise effects mediated by PTENP1 transcripts within intricate regulatory networks involving molecular interactions with PTEN and tumorigenicity in hepatocellular carcinoma (HCC) remains elusive." (PMID 29296207, 2017). "We aimed to elucidate the diagnostic efficacy of eight serum lncRNAs HULC, MALAT1, Linc00152, PTENP1, PTTG3P, SPRY4-IT1, UBE2CP3, and UCA1 and their combinations for the diagnosis of hepatocellular carcinoma (HCC)." (PMID 32733618, 2020).
bladder cancer (23 papers, 2018 to 2026). "Thus, exosomal PTENP1 has been recommended as a putative marker for diagnostic purposes in bladder cancer." (PMID 35655204, 2022). "Interestingly, we found that exosomal PTENP1 levels were downregulated in patients with bladder cancer, and lower exosomal PTENP1 expression was associated with higher tumor and clinical grade, as well as more advanced stage." (PMID 30285771, 2018). "The study demonstrates that PTENP1 regulates various cellular processes, including cell viability, migration, apoptosis, and cisplatin resistance, in cisplatin-resistant bladder cancer cells." (PMID 41362671, 2026). "Introducing PTENP1 into cisplatin-resistant bladder cancer cells through transfection inhibited their proliferation and migration, enhanced apoptosis, and decreased their resistance to cisplatin." (PMID 41362671, 2026). "The study suggests that exosomal PTENP1 from normal cells can be transferred to bladder cancer cells, reducing their malignant behavior both in vitro and in vivo." (PMID 40395335, 2025). "BMSC-derived exosomes can transport lncRNA PTENP1 into bladder cancer cells, and lncRNA PTENP1 inhibits the malignant phenotype of bladder cancer cells by regulating the miR-17/SCARA5 axis." (PMID 40647484, 2025). "Exosomes derived from PTENP1-overexpressing BMMSCs abolished the promotion of miR-17 overexpression or SCARA5 knockdown on the malignant phenotype of bladder cancer cells." (PMID 38994350, 2024). "In a study that aimed to investigate the role of exosomal lncRNA PTENP1 in bladder cancer, exosomal PTENP1 was found to mediate communication between cells in the tumor microenvironment by transferring PTENP1 from normal cells to bladder cancer cells." (PMID 36605618, 2023). "Studies have reported that the expression of exosome-lncRNA H19 in serum of bladder cancer patients is upregulated, and exosome-lncRNA PTENP1 in plasma is downregulated, both of which can serve as good tumour markers for bladder cancer diagnosis." (PMID 37592177, 2023). "Expression of PTENP1 has also been shown to be diminished in bladder cancer tissues as well as exosomes extracted from plasma samples of these patients." (PMID 35655204, 2022). "In order to promote the expression of SCARA5, exosomal lncRNA PTENP1 sponges miR-17 to prevent bladder cancer cell malignant behaviors as the mechanism." (PMID 36684446, 2022). "Exosomal levels of PTENP1 have the potential to discriminate bladder cancer patients from healthy subjects with area under receiver characteristic curve of 0.743." (PMID 35655204, 2022). "Exosomal long non-coding RNA (lncRNA) PTENP1, which is released by hBM-MSCs, inhibits the aggressive phenotypes of Bladder cancer cells (5637 and T24) by controlling the miR-17/SCARA5 axis." (PMID 36684446, 2022). "The PTENP1/miR-20a/PTEN molecular route has been shown to affect malignant behavior of bladder cancer cells." (PMID 35655204, 2022). "In bladder cancer cells, PTENP1 target miR-20a has been shown to be up-regulated, while PDCD4 has been down-regulated." (PMID 35655204, 2022). "A recent study reported that exosomes–transmitted long non-coding RNA PTENP1 suppresses bladder cancer progression by suppression PTEN expression." (PMID 34521440, 2021). "For instance, exosomes from normal cells transfer PTENP1 to bladder cells to block the progression of bladder cancer." (PMID 32602848, 2020). "Lin and his colleagues demonstrate that normal cells secrete exosomal PTENP1 and transmit it to bladder cancer (BC) cells to inhibit their malignant behaviors through the upregulation of PTEN by competitively binding to miRNA-1747." (PMID 32242003, 2020). "In the current study, we attempted to detect the biological role of PTENP1 in vitro, because we found that the downregulated expression of PTENP1 in bladder cancer tissues and exosomes from bladder cancer plasma." (PMID 30285771, 2018). "Meanwhile, animal experiments also supported the tumor suppressor function of PTENP1 in bladder cancer." (PMID 30285771, 2018).
bladder cancer (continued). "Nevertheless, no data are currently available regarding the biological roles of exosomal PTENP1 in bladder cancer." (PMID 30285771, 2018). "We identified that PTENP1 was mainly in exosomes, and found that PTENP1 was downregulated in bladder cancer tissues and plasma." (PMID 30285771, 2018). "To further explore the role of PTENP1 overexpression and exosomal PTENP1 in bladder cancer in vivo, we injected EJ cells with PTENP1/ NC lentiviral vector or PTENP1/NC Exos derived from 293A cells transfected with PTENP1/ NC lentiviral vector into nude mice." (PMID 30285771, 2018). "Together, our results revealed that exosomal PTENP1 serves as a mediator in cell-cell communication during carcinogenesis of bladder cancer." (PMID 30285771, 2018). "Our results revealed that PTENP1 was significantly decreased both in bladder cancer tissues and exosomes from bladder cancer plasma." (PMID 30285771, 2018). "In conclusion, our results indicated that exosomal PTENP1 was a promising novel biomarker for diagnosis of bladder cancer." (PMID 30285771, 2018). "Moreover, PTENP1 is transferred via small vesicles from normal cells to bladder cancer cells both in vitro and in vivo, with positive results indicating decreased tumor progression." (PMID 40877546, 2025). "Additionally, exosomal PTENP1 has been transferred from normal cells to bladder cancer cells, which resulted in a reduction in the progression of bladder cancer in vitro and in vivo." (PMID 37894321, 2023). "Exosomal MALAT1, PCAT-1 and PTENP1 have been found in many studies focused on the link between exosomes and bladder cancer, indicating these three molecules participate in the progression of bladder cancer in depth." (PMID 37805491, 2023). "The reduced expression of lncRNA PTENP1 in plasma-derived sEVs in patients with bladder cancer may serve as a potential marker for BC." (PMID 36612097, 2022). "For example, higher urinary exosomal LNMAT2, higher urinary and serum exosomal circPRMT5, higher serum exosomal UCA1, the PCAT-1, UBC1, SNHG16 panel, higher plasma exosomal H19 and lower plasma exosomal PTENP1 were more frequently observed in bladder cancer patients than in healthy controls." (PMID 32517366, 2020). "Meanwhile, PTENP1 could suppress bladder cancer progression by regulating miR-17 as well as esophageal squamous cell carcinoma." (PMID 32185172, 2020). "Interestingly, PTENP1-Exos also elevated the expression of PTEN in bladder cancer cells by western blot." (PMID 30285771, 2018). "All these results indicated that exosomal PTENP1 might act as a useful biomarker for discriminating patients with bladder cancer from healthy controls." (PMID 30285771, 2018). "In addition, normal cells released exosomes containing PTENP1, and that exosomal PTENP1 was transported from normal cells to bladder cancer cells, and exogenous PTENP1 relieved the malignant phenotype of bladder cancer cells both in vitro and in vivo." (PMID 30285771, 2018). "Although exosomes can package into long non-coding RNAs (lncRNAs) to mediate extracellular communication, the role of exosomal lncRNA PTENP1 in bladder cancer (BC) remains unclear." (PMID 30285771, 2018). "Hence, our findings suggest that PTENP1 is directly transferred from normal cells to bladder cancer cells via exosomes and regulate the biological functions of bladder cancer in vitro and in vivo." (PMID 30285771, 2018). "The purpose of this study was to find a potential biomarker that could be used in the diagnosis of bladder cancer, and investigate if exosomal PTENP1 intervenes in cell-cell communication, which may result in the progression of bladder cancer." (PMID 30285771, 2018). "Although our ROC analyses revealed that exosomal PTENP1 could be useful in detecting bladder cancer, we needed to further analyze large samples to evaluate its diagnostic accuracy." (PMID 30285771, 2018).
bladder cancer (continued). "Our results showed that PTENP1-Exos from 293A cells enhanced PTENP1 expression and suppressed proliferation, migration and invasion of bladder cancer cells; in addition, it induced apoptosis in bladder cancer cells." (PMID 30285771, 2018). "Therefore, further studies should be performed to comprehensively investigate the biology of intercellular PTENP1 and exosomal PTENP1 involved in bladder cancer development and progression." (PMID 30285771, 2018). "Thus, we speculated that PTENP1 may act as a ceRNA, participating in tumorigenesis of bladder cancer." (PMID 30285771, 2018). "The relationship between PTENP1 and the miR-103a/PDCD4 pathway offers a promising targeted therapy option for patients with bladder cancer that is resistant to cisplatin." (PMID 41362671, 2026). "Conversely, some EVs deliver lncRNAs such as PTENP1, which function as competing endogenous RNAs (ceRNAs), sponging miR-17 and thereby restoring PTEN expression in recipient bladder cancer cells." (PMID 40877546, 2025). "Additionally, this study showed that normal cells could package PTENP1 into exosomes and secrete it into bladder cancer cells, which significantly suppressed malignant behaviors of bladder cancer cells by decreasing the ability to proliferate, invade and migrate." (PMID 30285771, 2018). "The expression of H19, SNHG16 and UCA1 was significantly elevated in bladder cancer tissues, while PTENP1 and MEG3 were significantly decreased in bladder cancer tissues compared with adjacent normal tissues (P < 0.05)." (PMID 30285771, 2018). "This study showed that H19, SNHG16, UCA1, PTENP1 and MEG3 were aberrantly expressed in bladder cancer tissues." (PMID 30285771, 2018). "Thus, exosomal PTENP1 could be a potential candidate of bladder cancer detection." (PMID 30285771, 2018). "Analysis of serum exosomes from bladder cancer patients who did not respond to cisplatin treatment revealed that the expression of the PTENP1 gene was lower compared with patients who responded to the therapy." (PMID 41362671, 2026). "In addition, we confirmed that exosomal PTENP1 protected PTEN and suppressed biological malignant behavior of bladder cancer by sponging miR-17." (PMID 30285771, 2018). "In the present study, we enrolled a total of 12 major lncRNAs with important roles in multiple tumors until December 2016, among which Kcnq1ot1 and PTENP1 have not been investigated in bladder cancer." (PMID 30285771, 2018). "The frequent silencing of PTENP1 in patients with bladder cancer and bladder cancer cell lines but not in controls indicates that PTENP1 may act as a tumor suppressor." (PMID 30285771, 2018). "Furthermore, exosomal PTENP1 may act as a miR-17 decoy to regulate PTEN and suppress bladder cancer progression." (PMID 30285771, 2018).
prostate carcinoma (19 papers, 2015 to 2025). A carcinoma that arises from epithelial cells of the prostate gland. "PTENP1, a lncRNA, is found to be associated with prostate cancer in both database LncRNADisease and Lnc2cancer." (PMID 33980147, 2021). "Such controversy has, however, been recently cleared somewhat by evidence of PTEN and PTENP1 functioning as ceRNAs in studies using CRISPR knockdown and silencing of PTEN and PTENP1 in DU145 prostate cancer cells." (PMID 37894321, 2023). "In prostate cancer, the pseudogene PTENP1 functions as a ceRNA to regulate PTEN expression by sponging miR-499-5p." (PMID 35430805, 2022). "Knockdown of both genes is translated into growth acceleration, while upregulation of PTENP1 is enough to promote growth suppression in prostate cancer." (PMID 35054945, 2022). "Meanwhile, the expression of PTENP1 is correlated with PTEN in clear-cell renal cell carcinoma (ccRCC) and prostate cancer, and PTENP1 exert a growth-suppressive role by functions as a competing endogenous RNA (ceRNA)." (PMID 29291003, 2017). "The pseudogene PTENP1 has been hypothesized to be biologically active in prostate cancer cells by competitively binding to miR-17, miR-19, miR-21, and miR-26 families to regulate the cellular levels of PTEN and exert a growth-suppressive effect." (PMID 32615935, 2020). "Fluctuating levels of PTEN/PTENP1 are often correlated in prostate cancer samples and deletion of PTENP1 occurs frequently in some sporadic cancers such as endometrial, colon and prostate cancers, attributing a tumour suppressor function to PTENP1, that is independent of its regulation of PTEN." (PMID 29455665, 2018). "Some studies revealed PTENP1 may act to suppress prostate cancer." (PMID 36360269, 2022). "In prostate cancer, the competition between PTENP1 and PTEN for binding with their shared miRNAs, positively regulates PTEN protein levels, placing PTENP1 in the category of tumor-suppressor lncRNAs." (PMID 33142861, 2020). "The 3’UTR sequences of PTEN and PTENP1 share common putative microRNA binding site and overexpression of miR-19b and miR-20a in the prostate cancer cell line DU145 resulted in decreased PTEN and PTENP1 mRNA levels." (PMID 32314732, 2020). "Pseudogene PTENP1 was mostly elucidated and was reported to regulate cellular levels of PTEN and exert a growth-suppressive role in prostate cancer cell." (PMID 30219035, 2018). "PTENP1 3′ UTR over-expression resulted in the growth inhibition of cancer cells, suggesting that PTENP1 plays a tumour suppressive role in prostate cancers." (PMID 28112249, 2017). "Overexpression of miR-19b and miR-20a in prostate cancer cells resulted in a significant decrease in PTEN and PTENP1 mRNA transcription." (PMID 26335297, 2015). "To date, many reports have pointed out that the inhibitory role of PTENP1-PTEN genes is not exclusive to prostate cancer, and it is extensible to several type cancers such as colorectal cancer, breast cancer, or oral squamous cell carcinoma." (PMID 35054945, 2022).
clear-cell renal cell carcinoma (17 papers, 2015 to 2023). "They found that PTENP1 was downregulated in clear-cell renal cell carcinoma and overexpression of PTENP1 reduced cell proliferation, migration, invasion in vitro and tumor growth and metastasis in vivo." (PMID 32185172, 2020). "Of interest, PTENP1 can sensitize clear-cell renal cell carcinoma cells to cisplatin and gemcitabine treatments." (PMID 30071685, 2018). "PTENP1 is also downregulated in clear-cell renal cell carcinoma tissues, and its expression is positively correlated with PTEN expression." (PMID 30071685, 2018). "A lncRNA panel including lncRNA-LET, PVT1, PANDAR, PTENP1, and linc00963, were identified to distinguish clear cell renal cell carcinoma from healthy controls." (PMID 29029437, 2017). "For instance, PTENP1 has been found to be downregulated in clear-cell renal cell carcinoma tissues and cells due to methylation, and it suppressed cancer progression by functioning as a ceRNA through acting as a decoy for miR-21." (PMID 28881724, 2017). "Deletion of PTENP1 has been reported to downregulate PTEN expression in breast and colon cancer and melanoma, and downregulation of PTENP1 through methylation of its promoter sequence in clear-cell renal cell carcinoma suppresses cancer progression." (PMID 28558813, 2017). "And we were preparing this manuscript pseudogene PTENP1 functions as a competing endogenous RNA to suppress clear cell renal cell carcinoma progression." (PMID 26461224, 2015). "For instant, pseudogene PTENP1 could suppress the progression of clear-cell renal cell carcinoma by functioning as a ceRNA." (PMID 33378744, 2020). "Additionally, PTENP1 could mediated miR-21 expression and decreased the proliferation ability of oral squamous cell carcinoma and clear-cell renal cell carcinoma." (PMID 32185172, 2020). "In clear-cell renal cell carcinoma (ccRCC), PTENP1 could suppress tumour growth and migration." (PMID 28112249, 2017).